MCL1 (MCL1 apoptosis regulator, BCL2 family member)
Diseases named in the same sentence as MCL1 in open-access papers (continued):
Sharing a sentence is not in itself a finding about the gene and the disease.
cancer (continued). "Due to the non-specific binding properties of the PAPs with Mcl1, developing high-affinity inhibitors—both small molecule and peptide—that can restore apoptotic activity and inhibit cancer cell progression remains a considerable challenge." (PMID 32731448, 2020). "Like vincristine, we could detect an increase in priming with BAD, HRK, and MS1 BH3 peptides in CW9019 cells indicating that cancer cells also acquired resistance to doxorubicin treatment through BCL-xL and MCL-1." (PMID 32801295, 2020). "BCL-1, myeloid-cell leukemia (MCL-1), and B-cell lymphoma extralarge (BCL-XL) are antiapoptotic BCL-2 proteins frequently overexpressed in human cancer and protect cells against apoptosis under normal conditions in breast, prostate, and cholangiocarcinoma cancer cells." (PMID 32411231, 2020). "Mcl-1 overexpression confers acquired resistance to Bcl-2 inhibitors, and therefore we hypothesized that DYRK1A overexpression would also hinder the anti-cancer effects of Bcl-2 inhibitors." (PMID 32587776, 2020). "The SF3B1 inhibitor E7107 in combination with Bcl-xL/Bcl-2 inhibitors enhances cytotoxicity to cancer cells based on the evidence that E7107 alters splicing of MCL1, but not that of BCL2L1." (PMID 33064779, 2020). "Given the recent cardiac toxicities seen with MCL1 inhibitors, NOXA induction might be a suitable alternative to target MCL1 in cancer cells." (PMID 32824203, 2020). "MCL1, a member of the anti-apoptotic BCL-2 family, may be a treatment target in several cancers, including SCLC." (PMID 32152266, 2020). "Immunoblot analysis indicated that cancer cells receiving CM from paclitaxel-treated donors displayed an increased and long lasting expression of NOXA, a BH3-only protein essentially functioning as an endogenous MCL-1 inhibitor." (PMID 31937780, 2020). "We found that magnolol sensitizes TRAIL-induced apoptotic cell death via upregulation of DR5 and downregulation of cellular FLICE-inhibitory protein (c-FLIP) and Mcl-1 in cancer cells, but not in normal cells." (PMID 33050112, 2020). "Furthermore, by using S64846, an MCL-1-specific inhibitor, we found that MCL-1 inhibition in M2 CM-treated cancer cells increased apoptosis and decreased EMT marker expression." (PMID 32444799, 2020). "Combination therapy of navitoclax with other agents that target MCL-1 could restore the apoptosis process in cancers with high expression of BCL-XL and MCL-1." (PMID 33381025, 2020). "Indeed, CAFs-secreted IGF-binding proteins trigger the ERK/MAPK pathway in cancer cells and the subsequent inhibition of GSK3 that normally induces MCL-1 degradation." (PMID 33080792, 2020). "MCL1 is an important antiapoptotic member of the BCL-2 family, and the elevation of MCL1 protein level leads to chemoresistance and correlates with poor prognosis of cancer patients." (PMID 32699213, 2020). "In accordance with these recent data, we found in this study that genetic depletion of Fasn resulted in the lower growth rate of c-Myc/MCL1/Cre tumors as well as in the decrease of Cdk1, Cdk2, Skp2, and Survivin/Birc5 genes, which have been previously found to be regulated by FASN in cancer cells." (PMID 33187130, 2020). "Mcl-1 expression showed a statistically non-significant increasing trend related to poor survival and higher tumor grades and cancer stages." (PMID 33052877, 2020). "Not unpredictably, the downregulation of Mcl-1 increases cancer cell sensitivity to standard anticancer drugs, such as etoposide, doxorubicin, and ABT-737." (PMID 32260280, 2020). "NOXA is a BH3-only pro-apoptotic protein that has natural selectivity for MCL1; thus, although not directly binding to MCL1, these compounds were still able to sensitize cancer cells to other BH3 mimetics." (PMID 32824203, 2020). "In triple negative breast (TNBC) cancer cell lines, HHT was demonstrated to strongly decrease survival influenced by MCL-1, BCL-2, SURVIVIN, XIAP and could reduce cancer growth of MDA-MB-231 xenografts." (PMID 32151059, 2020).
cancer (continued). "As previously shown in other cancer cohorts, MCL-1 gains did not elicit compensatory dysregulation of other BCL-2 family members in LUAD, irrespective of the cohort analysed (TRACERx or TCGA)." (PMID 32913197, 2020). "We found that MCL1, Cofilin1 (CFL1) and SRC mRNA were highly expressed by a wide range of these cancers, suggesting that a strategy of dual MCL-1 and SRC inhibition might be efficacious for many patients." (PMID 31735913, 2020). "Since each long and short isoform of Mcl-1 and Bcl-X have anti- apoptotic/pro-apoptotic function in cancer cells, A2780 and HCT116 cells were used to determine whether T3 altered splicing to the apoptosis-related MCL1 and BCL2L1 genes." (PMID 33064779, 2020). "As OTUD1 regulates MCL1 protein levels, we tested whether OTUD1 influences the toxicity of a BH3 mimetic in cancer cells." (PMID 31467488, 2019). "Intriguingly, despite the development of another BH3 mimetic Obatoclax (GX15-070), which can also target MCL-1 in addition to BCL-2 and BCL-XL, and with its efficacy tested in various adult cancers, its effectiveness in childhood cancers was, nevertheless, not well-studied." (PMID 31652776, 2019). "In this case, MCL-1 dependency of cancers cells is not intrinsically driven but induced by CAFs from the microenvironment." (PMID 30631150, 2019). "The most effective Bcl-2 inhibitors ABT-737 and its analog ABT-263 target Bcl-2 and Bcl-xL; however, only weakly inhibited Mcl-1 thus are not effective against cancers with elevated Mcl-1 levels." (PMID 31404252, 2019). "A new BH3 mimetic, S63845, was recently found to selectively target MCL1, and S63845 has been tested in many preclinical models of human cancer, including breast cancer, but not in T-ALL." (PMID 30008477, 2019). "Additionally, MCL1 is known to cross-talk with multiple signal transduction pathways, e.g., EGFR and PI3K-AKT, thus cancer cells can utilize other survival mechanisms when MCL1 is suppressed, as possible resistance mechanisms." (PMID 31370269, 2019). "Thus, inhibitors of MCL1 appear especially attractive for combination with BCL-2 inhibitors for the treatment of T-ALL and other cancers." (PMID 30008477, 2019). "For instance, MCL1 transcription is activated by various transcription factors such as signal transducer and activator of transcription 3 (STAT3), STAT5, hypoxia-inducible factor 1 (HIF1), and E2F1 in a large variety of cancer types." (PMID 29361709, 2018). "To answer these questions, we developed a screening strategy to assess the sensitivity of cancer cell lines to all possible combinations of a selective BCL-2 inhibitor (ABT-199), a selective BCL-XL inhibitor (WEHI-539), and a selective MCL-1 inhibitor (A-1210477)." (PMID 30158527, 2018). "MCL-1 inhibitor S63845 efficiently kills MM and other MCL-1-dependent cancer cell lines." (PMID 30524962, 2018). "MCL1, one of the anti-apoptotic BCL-2 family members, is overexpressed in many human cancers, and in several key oncogenic pathways to sustain cancer cell survival and resist cancer treatment." (PMID 30139386, 2018). "Based on the fact that the combination therapeutic strategy showed great effect in TNBC, we inferred that it would also be effective in those cancers showing the same molecular profiles as TNBC, especially high expression of MCL-1 controlled by AKT/mTOR pathway." (PMID 29374168, 2018). "The authors found significantly reduced expression of miR-29a/b/a in PAS specimens and suggest this downregulation of miR-29a/b/c contributes to trophoblast cell survival by upregulating myeloid cell leukemia-1 (MCL1), an antiapoptotic protein known to play a role in cancer survival." (PMID 30057649, 2018).
cancer (continued). "Importantly, genetically forced expression or silencing of survivin, Mcl-1, XIAP, or cIAP2 in cancer cells, respectively, demonstrated their roles in mediating the action of FL118." (PMID 30285798, 2018). "Conversely, Mcl‐1 would be stabilised and apoptosis inhibited by a strategy targeting the APC/C directly, which might have less desirable consequences for cancer chemotherapy." (PMID 29987118, 2018). "In contrast, outside of a small number of studies in select cancer types, little is known regarding which cancers might respond well to single agent BCL-XL or MCL-1 inhibition." (PMID 30158527, 2018). "Interestingly, PTC596, reported to target cancer stem cells, decreased MCL-1 expression levels and antagonized ibrutinib-induced increase in MCL-1 expression, leading to synergistic apoptosis induction in MCL cells." (PMID 29983879, 2018). "It is known that survivin, Mcl-1, XIAP, and cIPA2 are strongly involved in treatment resistance of PDAC; survivin and Mcl-1 play important roles in cancer stem cell (CSC) drug resistance and function." (PMID 30285798, 2018). "Here we develop a drug screening approach to define the sensitivity of cancer cells from ten tissue types to all possible combinations of selective BCL-2, BCL-XL, and MCL-1 inhibitors and discover that most cell lines depend on at least one combination for survival." (PMID 30158527, 2018). "These FL118 efficacy results are consistent with our molecular-targeting data showing that FL118 inhibited the expression of multiple antiapoptotic proteins (survivin, Mcl-1, XIAP, cIAP2) and ERCC6, a critical regulator of DNA repair, in treatment-resistant pancreatic stem-like cancer cells." (PMID 30285798, 2018). "Because drug development specifically against MCL1 has been considerably slower, targeting USP13 to inhibit MCL1 indirectly is likely to represent an alternative approach to potentiate the therapeutic efficacy of ABT-263 in cancer cells." (PMID 29335437, 2018). "Targeting the druggable interface of Mcl-1-PUMA is promising to discover dual-acting compounds that could disrupt the interaction between Mcl-1 and PUMA, providing a way to settle the conflicts between effectiveness and side-effects of anti-cancer drugs." (PMID 28903337, 2017). "Based on the expression of Mcl-1 in ESCC tissue sample, we reasoned that Mc1-1 might play a role in ESCC cancer progression." (PMID 29383093, 2017). "Mcl-1 and CDK9 inhibitors, however, have had limited success in cancer therapy." (PMID 28520795, 2017). "Interplay of MCL-1 and HIF-1α have shown to be variable in different tissues and cancers." (PMID 28404924, 2017). "While ABT263 efficiently inhibits Bcl-xL, Bcl-2 and Bcl-w, it fails to bind Mcl-1, which is also commonly up regulated in cancer cells." (PMID 28418907, 2017). "For example, chrysin, a major compound from Apis mellifera in Thailand, could sensitize A549 and HeLa human cancer cell lines to the apoptosis-inducing factor TRAIL by inhibiting STAT3 and downregulating Mcl-1." (PMID 28472978, 2017). "Our studies not only define the essential role of Mcl-1 in chemoresistance, but also for the first time link a key pro-survival Bcl-2 family member with the NOX protein family, both of which have significant ramifications in cancer progression." (PMID 28423654, 2017). "Moreover, PEITC enhanced the efficacy of CDDP by degrading Mcl-1 in SP cells, which implies that PETIC is a promising chemotherapy-sensitizing agent targeting cancer stem cells." (PMID 26848531, 2016). "ABT-263 and its structurally related compound ABT-737 are potent inhibitors of the anti-apoptotic proteins Bcl-2, Bcl-xL, and Bcl-w, but not of Mcl-1, and induce apoptosis in cancer cells." (PMID 27461218, 2016).
cancer (continued). "In this review, we addressed the recent developments in our understanding on the derangements in cancer cell glycolysis and glutaminolysis and on the role of Bcl-2 family proteins including Mcl-1, NOXA, Bad, etc., in the regulation of reprogrammed metabolism in cancer cells." (PMID 26791262, 2016). "We demonstrate here, in the context of aspirin treatment, activation of AMPK may positively regulate cancer cell proliferation and survival through Akt, ERK and MCL-1." (PMID 26918349, 2016). "Furthermore, YM155 also induced down-regulation of Mcl-1 and c-FLIP expression in other cancer cells." (PMID 27528031, 2016). "By comparing adherent and non-adherent cancer cell types, we validated Mcl-1 as a general and early target of UNBS1450." (PMID 26068790, 2015). "In a nanoparticulate formulation limiting its action to αvβ3, tetrac modulates integrin-dependent effects on gene expression in human cancer cell lines that include increased expression of a panel of pro-apoptotic genes and decreased transcription of defensive anti-apoptotic XIAP and MCL1 genes." (PMID 26041883, 2015). "Since cancer types with BCL2 and MCL1 amplification are more prone to inhibition of these proteins, we reasoned that significant frequency of BCL2L1 amplification in a particular cancer type may indicate dependency on BCL-XL for survival." (PMID 26134786, 2015). "The expression levels of Bcl-2 and Mcl-1 varied among the nine cancer cell lines, suggesting that it was not contributing to TRAIL resistance." (PMID 26506422, 2015). "Because cancer types with BCL2 and MCL1 amplification are more prone to inhibition of their respectively encoded proteins, we hypothesized that cancers with a significant frequency of BCL2L1 amplification would have greater dependency on BCL-XL for survival." (PMID 26134786, 2015). "Mcl-1 is finely regulated and targeting canonical signaling pathways with kinases inhibitors such as PI3K/AKT/mTOR and RAF/MEK/ERK inhibitors gave promising results and strongly sensitized cancer cells to ABT-737." (PMID 25627260, 2015). "MCL1 has been proposed to have a unique role among the pro-survival members of the BCL2 family that protect cells, and in particular cancer cells of diverse origins, against various anti-cancer treatments." (PMID 25749045, 2015). "Overexpression of anti-apoptotic or pro-survival proteins of the Bcl family such as Bcl 2, B-cell lymphoma-extra large (Bcl-xL), myeloid cell leukemia 1 (Mcl-1), Bcl-2-like protein 2 (BCL2L2 or Bcl-w) and Bcl-2-related protein A1 (A1/Bfl-1) has been reported to be present in cancer." (PMID 26563258, 2015). "Thus in multiple cancer cell types, the level at which USP9X is able to deubiquitylate and stabilise MCL1 dictates its anti-apoptotic function." (PMID 25672900, 2015). "IL-24 induces cancer selective apoptosis through interacting with endoplasmic reticulum (ER) chaperone protein BiP/GRP78, activating Fas/FasL signaling pathway, as well as reduction in myeloid cell leukemia-1 (Mcl-1) expression." (PMID 26554307, 2015). "This could serve as a mechanism for the sensitization since elevated levels of Bcl-2 and other proteins within the same family e.g. BCL-XL and MCL1 correlate with cisplatin resistance as well as tumor recurrence in NSCLC and other cancers." (PMID 26353782, 2015). "Thus, SNS-032 sensitizes cancer cell lines to TRAIL-induced apoptosis by concomitant suppression of cFlip and Mcl-1." (PMID 24362439, 2014). "For example, the chromosome 1q cluster contained MCL1, a gene with a cancer driver signature based on Project Achilles (data not shown) but with a mean mRNA expression versus copy number correlation of 0.31." (PMID 24874471, 2014). "The decreased expression of death receptors TRAIL-R1 and TRAIL-R2 and antiapoptotic proteins (Bid, Bax, Bak, Smac/DIABLO) or increased expression of antiapoptotic proteins (FLIP, Bcl-2, Bcl-xL, Mcl-1, Akt, IAP-1, IAP-2, XIAP, survivin) in cancer cells were involved in TRAIL-resistance." (PMID 23573148, 2013).
cancer (continued). "In addition, miRNA-29-a is well known of oncosuppressor miRNA, which is frequently lost or down-regulated in cancer so that target oncoproteins like CDK6, MCL1, or BCL-2 can be upregulated." (PMID 24521303, 2013). "Unlike other antiapoptotic proteins, Mcl-1 has a very short half-life, allowing an opportunity to combat these cancers by rapidly sensitizing Mcl-1-dependent cancer cells to chemotherapy-induced apoptosis upon inhibition of Mcl-1." (PMID 23840208, 2013). "JY-1-106 induces cancer cell death regardless of the Mcl-1 expression levels through intrinsic apoptosis pathways, and sensitizes tumor cells to chemotherapeutic agents and to metabolic stress." (PMID 23680104, 2013). "In our previous studies, we found that gemcitabine could enhance ubiquitination and the subsequent degradation of Mcl-1, therefore exhibited synergistic cytotoxicity with ABT-737 in multiple types of cancer cells." (PMID 23284992, 2012). "In AML, miR-29 expression is negatively correlated with MCL-1 mRNA, while in HCC BCL-2 and MCL-1 were both direct targets of miR-29; both of these findings support the theory that miR-29 functions as a tumor suppressor in cancer by promoting apoptosis." (PMID 23335942, 2012). "Four functional SNPs in the promoter of NOXA (rs9957673, rs4558496) and MCL1 (rs9803935, rs3738485) were genotyped for 380 cases and 335 frequency-matched cancer-free controls of non-Hispanic whites." (PMID 22548841, 2012). "To determine the impact of USP9X inhibition on cancer cell survival in our present experiments, we used its inhibitor WP1130 and found that the treated cells showed Mcl-1 downregulation which increased their sensitivity to ABT-737 as well as to other chemotherapeutic agents." (PMID 23171055, 2012). "The interplay between these factors may then be exploited by cancer cells, where activation of ERK and inactivation of GSK3/phosphodegron-mediated degradation would promote extended Mcl-1 stabilization and drug resistance." (PMID 23056582, 2012). "However, even in the presence of MCL1, ABT737 can exhibit preclinical activity in some cancers such as CLL, possibly due to constitutive occupancy due to priming for death." (PMID 22738201, 2012). "No significant decline in the levels of Mcl-1 and Bcl-2 was observed in the cancer cell lines where the overall levels remained relatively stable and even increased at 16–24 h of CHX treatment." (PMID 21730980, 2011). "We cannot formally rule out, however, that Mcl-1 contributes to the biology of cancer initiating cells by mechanisms other than regulation of cell survival stricto sensu." (PMID 21899728, 2011). "This is likely an important finding as, like BCL-2, MCL1 does not induce proliferation but rather promotes cancer cell viability by blocking apoptosis." (PMID 21625473, 2011). "A treatment in which quercetin would be combined to one or more Mcl-1 inhibitors may result in a significant improvement of therapy in both CLL and other types of cancer." (PMID 21750559, 2011). "Finally, we have identified a number of down-regulated miRNAs whose targets are up-regulated in cancer, including the oncogenic protein KRAS and MYCN, mitogen-activated protein (MAP) kinases and the anti-apoptotic proteins BCL2, BCL2L2 and MCL-1 among others." (PMID 20668671, 2010). "In addition to IL-6, the expression of cyclin D1, c-myc, survivin, Bcl2, Mcl1, and VEGF, all of which are regulated by Stat3 activity, and play a crucial role in apoptosis and progression of cancer, are also down regulated in response to avicin D." (PMID 19440292, 2009). "Importantly, the specificity of our antibodies to the three major BCL-2 family heterodimer protein complexes (i.e., BCL-2, MCL-1, and BCL-XL with BIM) that dictate cancer cell priming was validated here using both purified proteins and cells, including knockdown/knockout lines." (PMID 40507334, 2025).